AFP (alpha fetoprotein)
Diseases named in the same sentence as AFP in open-access papers (continued):
Sharing a sentence is not in itself a finding about the gene and the disease.
Cirrhosis (continued). "The serum levels of AFP in HCC patients, CHB-related cirrhosis patients and non-cirrhosis patients were 148.62 ± 303.99, 15.16 ± 7.06 and 8.27 ± 6.03, respectively (P < 0.001)." (PMID 28852419, 2017). "At last, age, gender, α-fetoprotein (AFP), γ-glutamyl transferase (GGT), hyaluronic acid (HA), Albumin and platelet (PLT) were included in the nomogram for cirrhosis." (PMID 29235488, 2017). "It is evident that the increase of AFP, AFP-L3, and ALT levels in serum and AFP-L3/AFP ratio are potential precursors of HCC; thus regular monitoring of these markers seems necessary in hepatic cirrhosis patients." (PMID 28540298, 2017). "We therefore wanted to compare the level of expression of these genes in EpCAM+ cells isolated from control (Ep+NSC), advanced cirrhosis (Ep+CIR) and AFP+ HCC tissues (Ep+HCC)." (PMID 28176469, 2017). "Receiver operating characteristic curve analysis of sAxl displayed a strongly increased sensitivity and specificity to detect both cirrhosis (80.8%/92.0%) and HCC (83.3%/86.7%) with an area under the curve of 0.935/0.903 as compared to AFP." (PMID 28526812, 2017). "AFP had a similar performance as S2-bound AGP with an AUC of 0.77 for differentiation of HCC and cirrhosis and an AUC of 0.82 for differentiation of HCC and hepatitis." (PMID 28296934, 2017). "The RFS was compared for nine putative prognostic factors, including age, gender, presence of cirrhosis, nodule numbers, macroscopic tumor thrombi, microvascular invasion, histological grading, CK19/GPC3 expression pattern, and AFP-CV." (PMID 28276470, 2017). "We assessed the performance of serum MDK, OPN, DKK1 and AFP alone or in combination for the diagnosis of HCC, as compared to their serum levels in patients with cirrhosis, chronic liver disease or healthy controls." (PMID 27219517, 2016). "For that reason, the Alaska Native Tribal Health System has screened all persons with CHB for HCC by semi-annual serum AFP measurements; only persons with an elevated AFP and persons with a family history of HCC or cirrhosis were referred for US." (PMID 27197711, 2016). "Once cirrhosis is established, HCC develops at an annual rate of 1–4 % and is increased in patients with raised alpha-fetoprotein levels at baseline." (PMID 27229718, 2016). "We also analyzed the complementary properties of using CCT3 and IQGAP3 in combination with AFP for the diagnosis of HCC, using a logistic regression model,with “0” represents the cirrhosis group, “1” represents liver cancer." (PMID 27390551, 2016). "Actuarial DFS and CDFS3 rates were stratified by different clinicopathologic variables such as age, sex, viral hepatitis, cirrhosis, Milan criteria, AJCC stage, differentiation, microvascular invasion, capsule, AFP, tumor number, and tumor size." (PMID 27495049, 2016). "Alpha-fetoprotein (AFP) produced by primary hepatic cancer is different from that generated by hepatitis, hepatic cirrhosis, and other benign hepatic diseases with respect to the carbohydrate chain." (PMID 27528397, 2016). "Similarly, measurement of serum alpha-fetoprotein (AFP) has long been proposed as a diagnostic marker of HCC, but it fails to diagnose approximately one-third of patients with early-stage HCC and is also found elevated in benign liver diseases, such as hepatitis and cirrhosis." (PMID 26950158, 2016). "However, AFP has a suboptimal performance as a serological test for surveillance for 2 reasons; firstly, fluctuating levels of AFP in patients with cirrhosis might reflect flares of HBV or HCV infection, exacerbation of underlying liver disease or HCC development." (PMID 25737783, 2015). "Next, we compared gene expression profiles in young and old patient groups after adjusting for significant confounding factor such as Edmondson grade, etiology, cirrhosis, AJCC T stage, albumin level and AFP level." (PMID 26093092, 2015).
Cirrhosis (continued). "In contrast, no statistically significant relations were detected between miR-25 expression and factors such as age, gender, tumor size, portal vein invasion, AFP and HCC cirrhosis." (PMID 26460549, 2015). "In this study, we found that overexpression of AFP, AFPR and Src in cirrhosis and HBV-related HCC tissue samples, and showed that expression of AFPR and AFP prior to expression of Src during the progress of HBV-related hepatocarcinogenesis." (PMID 25943101, 2015). "High intratumoral EpCAM was significantly associated with more major vascular invasion (P = 0.023), high AFP (P < 0.001) and high Edmondson grade (P = 0.005), High intratumoral OV6 expression of the entire group demonstrated more cirrhosis (P = 0.015)." (PMID 25197550, 2014). "Levels of YB-1 and alpha fetoprotein (AFP) in serum samples from 105 HCC patients, 25 hepatitis B virus patients, 25 cirrhosis patients, and 50 healthy donors were detected using the established method and an AFP electrochemiluminescence kit." (PMID 24069038, 2013). "Alpha-fetoprotein (AFP) is widely used for HCC’s surveillance and detection test among patients with cirrhosis." (PMID 24143209, 2013). "This study revealed a significant increase in AFP serum levels in HCC and some benign liver diseases such as hepatitis and cirrhosis." (PMID 27335826, 2013). "Our data suggested that 5-mC and some clinico-pathological parameters (ALT, AST, ALT/AST, Tp, Alb, 5′NT, CHE, UA, RBP, AFP, PT, PT%, INR, DFbg and TT) were affected by cirrhosis or liver inflammation." (PMID 24143196, 2013). "However, AFP serum levels can also be increased in patients with other nontumorous hepatic disorders, including acute and chronic hepatitis of any type, cirrhosis, and/or massive hepatic necrosis, and may reflect (general) hepatic inflammatory and regenerative activity." (PMID 24455683, 2013). "The most important liver cancer serum biomarker is alpha-fetoprotein (AFP), an oncofetal glycoprotein with elevated levels in patients affected by cirrhosis and HCC." (PMID 23401773, 2013). "The 8 subgroups of HCC patients were identified as ‘tumor multiplicity (multiple)’, ‘tumor size (≥5 cm)’, ‘HBsAg (positive)’, ‘serum AFP (≥20 ng/ml)’, ‘grade (III–IV)’, ‘cirrhosis (yes)’, ‘stage (III–IV)’, and ‘relapse (yes)’." (PMID 23272146, 2012). "The median AFP value determined in our patients with HCC and those with cirrhosis were 92.4 ng/ml and 5.96 ng/ml respectively." (PMID 18638391, 2008). "Serum AFP, PIVKA-II, GP3 and SCCA-1 levels were determined in 50 patients with HCC arising in a background of ALD or NAFLD cirrhosis." (PMID 18638391, 2008). "An increased concentration of AFP (i.e. 20 ng ml−1) was observed in 70 out of 120 (58.3%) patients with HCC and in 33 out of 90 (36.7%) patients with cirrhosis." (PMID 12799630, 2003). "An AFP concentration above 20 ng ml−1 was observed in 70 of 120 patients with HCC (58.3%) and in 33 of 90 patients with cirrhosis (36.7%)." (PMID 12799630, 2003). "When hepatic lesions occur without cirrhosis, washout, vascular invasion, or elevated AFP, PHA should be considered as an alternative diagnosis." (PMID 41594267, 2026). "Primary hepatic EST is an infrequent but important differential diagnosis of HCC, particularly in young women without cirrhosis who present with markedly elevated AFP levels." (PMID 41523302, 2026). "In patients with hepatitis and cirrhosis who were positive for AFP, no ESPL1 positivity was detected." (PMID 40248196, 2025). "In patients with cirrhosis 6-monthly ultrasound and AFP testing should be undertaken, while in those without cirrhosis annual ultrasound and AFP levels are appropriate." (PMID 41270865, 2025). "There was no apparent reason for raised AFP in these subjects, such as alcohol abuse, hepatitis, cirrhosis, biliary tract obstruction, and Fanconi anaemia, and there was no GCT relapse in these patients." (PMID 39934683, 2025).
Cirrhosis (continued). "Current data indicate AFP demonstrates suboptimal sensitivity (∼60 %) and specificity (∼80 %), with particular shortcomings in detecting early-stage HCC and distinguishing malignant lesions from benign liver conditions such as cirrhosis or chronic hepatitis." (PMID 40678800, 2025). "HCC remains a leading cause of cancer-related mortality, and current AASLD/EASL guidelines recommend semi-annual surveillance in patients with cirrhosis, typically using ultrasound with or without serum alpha-fetoprotein (AFP)." (PMID 41369398, 2025). "Annual abdominal ultrasound and semiannual alpha-fetoprotein (AFP) measurements may be reserved for children with a concern for advanced liver disease, family history of early cirrhosis, HCC, or evidence of rapid disease progression." (PMID 40019674, 2025). "Among patients with cirrhosis versus those without, AFP was higher in the cirrhotic group (210 vs. 150 ng/mL, p=0.044) and liver stiffness was markedly elevated (20.0 vs. 8.5 kPa, p<0.001)." (PMID 40308490, 2025). "Although increased serum AFP levels are associated with increased levels of hepatic inflammation and fibrosis, which are highest in patients with cirrhosis, the clinical significance of elevated AFP in CHC patients has not been clearly demonstrated." (PMID 40384539, 2025). "Compared with patients with no NUGs, those patients with one or two NUGs had a worse OS in the subgroup of aged ≤ 47, male, never smokers, never drinkers, with AFP level > 400 ng/mL, with cirrhosis, no embolus, and with BCLC stage B/C (P < 0.05 for all)." (PMID 39090420, 2025). "The American Association for the Study of Liver Diseases surveillance guidelines recommend ultrasound surveillance with or without alpha-fetoprotein testing on a semi-annual basis in anyone with cirrhosis because of demonstrated improvements in survival." (PMID 40546598, 2025). "Alpha-fetoprotein (AFP) remains the most widely used serum biomarker in HCC surveillance; however, its sensitivity for early-stage disease is limited, and levels can be elevated in chronic hepatitis or cirrhosis." (PMID 41007803, 2025). "Various baseline characteristics, including age, sex, BMI value, AFP levels, presence of HBV and cirrhosis, portal hypertension, Child–Pugh grade, ablation method, and tumor proximity to large vessels or subcapsular hepatic, were subjected to statistical analysis." (PMID 40272237, 2025). "Finally, prospective multicenter trials should evaluate liquid biopsy applications, particularly for the 14-gene HBV signature (ABCA8, S100P) and 164 cirrhosis-to-HCC transition markers, benchmarked against current standards like AFP." (PMID 40678800, 2025). "Thus, for the differential diagnosis between CHB/Cirrhosis and HCC, ROC curves were constructed to assess the predictive potential of miR-200a-3p and AFP." (PMID 41459517, 2025). "Despite these challenges, PEComas should be considered in cases of solitary liver lesions in patients without cirrhosis and with negative AFP, even if the washout sign is present." (PMID 40723161, 2025). "While mild AFP elevations (typically <100 ng/mL) can occur in non-malignant conditions such as cirrhosis, chronic hepatitis, pregnancy, or germ cell tumors AFP levels are usually normal in FNH." (PMID 40882288, 2025). "Nonetheless, our study is among the first to directly compare GAAD and GALAD to ultrasound plus AFP in a non-viral cirrhosis population." (PMID 41375033, 2025). "Approximately 40% of HCC patients are AFP-negative, and elevated AFP levels can also occur in non-neoplastic liver diseases, such as cirrhosis, acute hepatitis, and viral hepatitis, thus limiting its reliability." (PMID 40426850, 2025). "In a study with 96 patients, including 58 with cirrhosis and 38 with early-stage HCC, the combination of LC-SPIK and AFP increased the AUC of the LC-SPIK test from 0.841 to 0.897, an increase of 0.056; for AFP, the AUC increased from 0.719 to 0.897, an increase of 0.178 (LC-SPIK + AFP)." (PMID 38611638, 2024).
Cirrhosis (continued). "GP73 was found to be superior to AFP in differentiating HCC from cirrhosis, but not superior to AFP for early HCC diagnosis." (PMID 38672535, 2024). "The AFP absolute values were also correlated with cirrhosis etiology, without a difference in median AFP between patients with viral etiology vs. others (18 ng/mL vs. 13 ng/mL, respectively; p = 0.096)." (PMID 38792876, 2024). "In addition, we assessed publication bias in terms of clinicopathological characteristics, including age, gender, histological grade, vein invasion, cirrhosis, tumor number, tumor size, HBV infection, PVTT, tumor stage, and AFP." (PMID 38634194, 2024). "Subgroup analysis further validated that the presence of ADs in HCC patients rendered no significant adverse impact on liver-specific mortality nor recurrence, regardless of age, cirrhosis, serum AFP level, hemoglobin level and tumor size." (PMID 39031214, 2024). "To investigate whether the effect of the combined risk genotypes on HBV‐HCC OS was confounded by age, sex, smoking status, smoking status, drinking status, cirrhosis, cancer embolus, BCLC stage and AFP, we performed stratified analysis in the combined dataset." (PMID 39163514, 2024). "Cirrhosis was more common in the HCC group (48.9% vs 28.2% in ICC lesions), whereas the serum tumor marker of CA19-9 was higher in the ICC patients (35.5% vs 21.6% in HCC lesions, p=0.003), while AFP was significantly lower in ICC than in HCC (P=0.005)." (PMID 38817871, 2024). "Forest plot analysis of OS and PFS indicated that the IT + TACE group gained survival benefits across almost all subgroups, compared with IT alone, especially in subgroups categorized by AFP level, PVTT classification, cirrhosis, and MRI arterial enhancement, in line with previous studies." (PMID 39335637, 2024). "All misdiagnosed cases had no history of hepatitis or cirrhosis, and liver tumor markers such as AFP were not elevated." (PMID 38807765, 2024). "A recent study suggests that GALAD is more sensitive and specific than AFP in detecting preclinical HCC, and use of GALAD may prevent unnecessary MRI or CT (computerized tomography) tests in up to 54% of patients with cirrhosis." (PMID 37144952, 2023). "AFP is one of the most widely used serological markers for HCC, but its sensitivity and specificity are not perfect due to the elevation of its levels in patients with cirrhosis and active hepatitis." (PMID 37946141, 2023). "AFP serum values were often elevated in patients with chronic liver disease or cirrhosis without HCC." (PMID 36899960, 2023). "AFP was 36.45, 49.14 or 2319.21 μg/l from CHB, HBV-cirrhosis or HBV-HCC patients, respectively." (PMID 35347503, 2023). "Current surveillance strategies in patients with cirrhosis involve ultrasound every 6 months, with or without monitoring alpha-fetoprotein (AFP) levels, the existing clinical biomarker of disease activity for HCC." (PMID 37760495, 2023). "This suggests that the age, TBIL, ALT, ALB, PT, GGT, and GPR are useful for identifying patients with AFP-negative non-liver disease, hepatitis, cirrhosis, and HCC but are of limited value." (PMID 36890811, 2023). "Using elevated AFP to diagnose HCC is controversial largely due to low sensitivity and specificity, particularly AFP expression is affected by patients with pre-existing liver diseases, such as cirrhosis and chronic hepatitis B virus." (PMID 36832164, 2023). "In the subgroup of AFP‐negative HCC patients without cirrhosis after liver resection, the TPS model continued to demonstrate its efficacy in effectively stratifying OS (p < 0.001) and early recurrence (p < 0.001)." (PMID 38130028, 2023). "Currently, early screening for LC mainly relies on abdominal ultrasonography and serum alpha-fetoprotein (AFP) testing, which have relatively limited sensitivity, especially in patients without cirrhosis." (PMID 38126999, 2023). "Nevertheless, not all HCCs secret AFP, and the elevation of AFP can be observed in cirrhosis or hepatitis cases." (PMID 38023207, 2023).
Cirrhosis (continued). "The levels of AFP were significantly higher in HBV-HCC than CHB, HBV-cirrhosis (p < 0.01)." (PMID 35347503, 2023). "Based on the AFP ratio, BCLC stage and cirrhosis diagnosis, a satisfactory nomogram was developed." (PMID 37124520, 2023). "AFP, on the other hand, is not only recommended by several guidelines for monitoring liver cancer, but it also increases the chance of detecting HCC early on in patients with cirrhosis or chronic hepatitis C when assessed serially alongside liver ultrasounds." (PMID 37370914, 2023). "At present, society guidelines recommend HCC primary surveillance for patients with chronic hepatitis B (CHB) and cirrhosis, based on abdominal ultrasound (US) evaluation with or without serum alpha-fetoprotein (AFP) levels." (PMID 37627125, 2023). "HCC occurred in 16 patients (5.3%) within six years post-SVR; these patients were older and had higher cirrhosis prevalence, alpha-fetoprotein levels, and fibrosis-4 index scores than did those without HCC development." (PMID 37629725, 2023). "The nomogram included three variables, namely, AFP ratio, BCLC stage, and cirrhosis." (PMID 37124520, 2023). "In the subgroup analysis of AFP‐negative HCC patients with cirrhosis after liver resection, the TPS model had a higher AUC and a higher C‐index in predicting early recurrence, but the results of the DeLong's test showed no statistical significance." (PMID 38130028, 2023). "No agreement exists regarding the addition of alpha fetoprotein, though this combination has been estimated to be more cost‐effective than ultrasound alone in people with compensated cirrhosis." (PMID 37877338, 2023). "Only 47.1% (n = 32) of patients without cirrhosis had a raised AFP (≥7) compared to 60.8% (n = 124) of patients with cirrhosis who had a raised AFP level (p = 0.047)." (PMID 37958389, 2023). "In the subgroup of AFP‐negative HCC patients with cirrhosis after liver resection, the TPS model was also able to stratify OS and early recurrence (OS: p < 0.001; early recurrence: p = 0.007)." (PMID 38130028, 2023). "For patients with decreased AFP after 8 weeks of curative treatment of HCC based on hepatitis/cirrhosis but without normalization, AFP-L3 decreased to < 10% indicates effective treatment." (PMID 37369911, 2023). "In HCC surveillance, the international guidelines suggest a six months abdominal ultrasound (US), with or without alpha-fetoprotein (AFP) evaluation, in patients with cirrhosis and in a subgroup of patients with chronic hepatitis B infection." (PMID 36831120, 2023). "The level of AFP elevates in three conditions: liver cancer or testicular cancer, pregnancy, and sometimes in non-cancerous diseases such as cirrhosis and hepatitis." (PMID 36793354, 2023). "Guidelines from the American Association for the Study of Liver Diseases (AASLD) recommended that individuals with cirrhosis undergo HCC surveillance through ultrasonography with or without alpha-fetoprotein (AFP) every 6 months." (PMID 37835478, 2023). "The presence or absence of cirrhosis with tumour features, including vascular invasion and portal vein thrombosis, tumour size and alpha-fetoprotein, are important prognostic indicators of HCC, which affects treatment decisions and outcomes." (PMID 35602894, 2022). "High levels of AFP can indicate liver cancer, ovarian or testicular cancer, and non-cancerous liver disorders such as cirrhosis and hepatitis." (PMID 36577761, 2022). "Its combination with AFP had higher sensitivity to diagnose HBV-related HCC compared with patients with cirrhosis, healthy patients, and patients with no HCC but accompanied by poor specificity." (PMID 36203765, 2022). "In the derivation set, twenty-two variables, including age, sex, HBsAg, hepatitis C, cirrhosis, tumor number, largest nodule diameter, capsule, APRI, FIB-4, NLR, WBC, haemoglobin, platelet count, MPV, PDW, AST, ALT, γ-GGT, total bilirubin, AFP, and CA19-9 entered into the original model." (PMID 35668355, 2022).